APOE (apolipoprotein E)
Diseases named in the same sentence as APOE in open-access papers (continued):
Sharing a sentence is not in itself a finding about the gene and the disease.
cancer (continued). "Prior studies have identified the impact of lifestyle-related factors on mediating the relationship between apoE isoform and long-term cancer-related toxicity." (PMID 36441715, 2022). "Genetic alterations of APOE were investigated across various cancer samples in the cohorts from TCGA." (PMID 37304007, 2022). "This novel pan-cancer study outlines the current understanding of APOE oncogenic roles across thirty-three cancers and highlights the complex association between AD and cancers." (PMID 37304007, 2022). "This pan-cancer analysis of APOE shows that the genetic alterations, protein phosphorylation, and DNA methylation of APOE has significant clinical relevance for survival prognosis and immune cell infiltration." (PMID 37304007, 2022). "The present study provides the first pan-cancer analysis of APOE across different cancers using datasets of the NCBI Gene Expression Omnibus (GEO) and TCGA." (PMID 37304007, 2022). "The present study carried out a thorough and necessary investigation of the specific effects of APOE on human cancers." (PMID 37304007, 2022). "Amplifications of APOE, the most frequent DNA alteration in the TCGA pan-cancer panel, were observed primarily in UCEC, OV, and BRCA patients." (PMID 37304007, 2022). "In this study, the mRNA expression levels of APOE were significantly increased for seven out of the top ten cancers containing genetic alterations, most of which were amplifications." (PMID 37304007, 2022). "In the present investigation we found APOE in the lists of Cancer Related and Extracellular Vesicles proteins, in both Newly Diagnosed and Recurrent pools and in all three zones." (PMID 35216175, 2022). "Among cancer samples, samples were divided into 2 groups (top 1/2 and low 1/2 APOE expression groups)." (PMID 35371313, 2022). "Here, we compared APOE expression in tumors and its corresponding control tissue across about 33 different cancers." (PMID 37304007, 2022). "In this study, we analyzed the potential immunoregulatory, cancer promoting and clinical value of APOE by bioinformatics." (PMID 35371313, 2022). "Future studies of the relationship of APOE genotype with long-term toxicity burden and functional outcomes in male cancer survivors enrolled in a clinical exercise trial are warranted." (PMID 36441715, 2022). "The present pan-cancer analysis of APOE shows that the protein phosphorylation, DNA methylation, and genetic alterations of APOE have a significant clinical relevance for survival prognosis and immune cell infiltration." (PMID 37304007, 2022). "All types of apoE isoforms upregulate, either commonly or individually, several pathways related to cancer and immune response, which implication in the biology of developing neurons is unclear." (PMID 35572125, 2022). "Among the target genes of miR-1908-5p, PTEN, DNAJA4, ApoE, and HDAC10 were associated with cancer cell invasion and metastasis." (PMID 35463352, 2022). "This study demonstrates that the expression level of APOE is statistically significantly related to gene expression of immunity-related genes across different cancers." (PMID 37304007, 2022). "This is the first examination of the relationship among exercise, apoE genotype, and side effects and symptoms of cancer in a subset of older female cancer survivors participating in a large clinical exercise trial." (PMID 36441715, 2022). "APOA1 and APOE are dysregulated in several tumors and interact with both the innate and adaptive immune system to sustain cancer cell proliferation." (PMID 36362243, 2022). "In this study, we investigated the oncogenic role of the APOE gene across cancers by GEO (Gene Expression Omnibus) and TCGA (The Cancer Genome Atlas)." (PMID 37304007, 2022).
cancer (continued). "The analyses of APOE demonstrated that the most common DNA alteration was the observed “amplification” of CNA from TCGA pan-cancer, as demonstrated using the cBioPortal website." (PMID 37304007, 2022). "Additional research is required to investigate the specific roles of APOE in different cancers and Alzheimer’s therapy." (PMID 37304007, 2022). "ApoA1 and ApoE are elevated in dormant cancer cell-derived extracellular vesicles and particles (EVPs), which can be a predictive biomarker for cisplatin resistance." (PMID 36506554, 2022). "We attempted to use APOE inhibitor (αAPOE, COG 133TFA, competing with the APOE holoprotein for binding the low-density lipoprotein (LDL) receptor) to test its therapeutic potential against carcinomas." (PMID 36147474, 2022). "Our analysis showed that APOE is differentially expressed in THCA patients according to cancer stage, race, age, nodal metastasis, and histological subtype." (PMID 33521130, 2021). "Differential expression of APOE was found in patients with different cancer stages and of different race, age, nodal metastatic status, and histological subtype." (PMID 33521130, 2021). "Our results align with an emerging picture of APOE ε4 status and cognitive outcomes in cancer populations, which suggests small but meaningful interactive effects." (PMID 34480030, 2021). "Astrocytes regulate the integrity and permeability of the BBB as well as immune and cancer cells infiltration via specific chemokine and cytokine network, angiotensin, apolipoprotein E (ApoE) and retinoic acid." (PMID 34200145, 2021). "Further, the interaction of APOE ε4 status and endocrine therapy are likely both mild and latent if cancer-related cognitive decline and endocrine therapy exposure represent advanced cognitive aging." (PMID 34480030, 2021). "LGALS3BP has been found in diverse cancer-derived exosomes, and APOE has been found in exosomes released from macrophages and neurons." (PMID 34660591, 2021). "The roles of apoE are different among various cancer tissues due to the regulation induced by upstream molecules." (PMID 32306242, 2020). "Apolipoprotein E overexpression has been reported in various cancers, such as gastric, lung, and prostate 20-22." (PMID 32368289, 2020). "By means of TWAS, we recovered seven genes (APOC1, APOE, BIN1, HMGB1, PRKAA1, SQSTM1, and UCP2) significantly associated to AD traits and some cancer models." (PMID 31608105, 2019). "The role of ApoE in cancer cells is unclear except that ApoE promoting cancer cell proliferation and migration." (PMID 31788012, 2019). "In vitro, NK cells from ApoE KO mice were more cytotoxic than those from WT mice in co-culture studies with NK cells and cancer cells." (PMID 31275318, 2019). "In this study, we incidentally found that plasma concentration of ApoE significantly decreased in cancer cachexia patients, which was the first report as far as we known." (PMID 31788012, 2019). "Related studies have revealed that ApoE activity on cancer cells is dual according to different tissues and ApoE affects several signaling cascades, including by increasing disabled phosphorylation and by activation of the ERK1/2 pathway." (PMID 30631342, 2018). "Even for cancer, as already found for APOE and Alzheimer's, studies indicate that there are positive aspects reported by patients about having undergone genetic testing." (PMID 30619456, 2018). "In cancer, ApoE expression has an inverse correlation with the stage, treatment response and prognosis." (PMID 29458390, 2018). "Whereas more cancer cells were attached to the tissues surfaces in ApoE−/− mice compared to WT controls, pre-treatment with BAPN robustly attenuated the adhesions compared to CTRL mice." (PMID 29458390, 2018). "In lung adenocarcinoma, ApoE over-expression promotes cancer proliferation and migration and is related to chemo-resistance." (PMID 30631342, 2018). "APOE is presented in multiple normal and cancer tissues, including normal human endometrium, EH, and ECa." (PMID 25741405, 2015).
cancer (continued). "The network is apparently related to oxidative stress (Nr2f2), cancer (Jun, Kras) and metabolic pathways (ApoE)." (PMID 23922661, 2013). "Recently, oral administration of the anti-cancer drug bexarotene has been shown to enhance clearance of soluble Aβ, through apoE-mediated mechanisms, and to reduce β-amyloid plaque deposits in mice, but is yet to be tested against human AD." (PMID 23382963, 2013). "Ligand receptor analysis revealed that APOE+ macrophages may interact with cancer cells via the SPP1‐CD44 and FN1‐SDC4/CD44 signaling pathways, whereas monocytes and DCs may interact with cancer cells via the LGALS9‐CD44 signaling pathway." (PMID 40492378, 2025). "APOE+ macrophages have been demonstrated to affect immunotherapy outcomes in cancer through hypothesized interactions with CD8+ T effector exhausted cells." (PMID 41279473, 2025). "These discrepancies may be attributed to the existence of different APOE isoforms, as distinct isoforms could exert either protective or inhibitory effects on cancer development." (PMID 39810624, 2025). "In contrast, in relation to cancer, variation in APOE does not appear to feature strongly in genetic risk factors for different types of cancer from various GWASs." (PMID 40149482, 2025). "In most recent studies, APOE was regarded as a cancer-promoting factor." (PMID 39990672, 2025). "Additionally, we found that APOE overexpression influenced multiple pathways related to metabolic remodelling and immunity, which are crucial for tumorigenesis and cancer progression." (PMID 39810624, 2025). "Conversely, in cancer, there is an absence of strong genetic evidence of risk for APOE in relation to the different cancers." (PMID 40149482, 2025). "In cancer, the role of ApoE may be more subtle, complex and yet clinically significant, with strong indications that it influences aspects of the cellular microenvironment that are critical for the development of cancer." (PMID 40149482, 2025). "Moreover, ApoE from macrophages induced apoptosis in breast tumor cells, further emphasizing a likely complex role in cancer development and progression." (PMID 40149482, 2025). "Apolipoprotein E (APOE), a gene involved in metabolism and immune regulation, is highly expressed in a macrophage subpopulation (APOE+ macrophages) that has been reported in multiple cancers and is associated with immunosuppression and enhanced invasiveness." (PMID 40736341, 2025). "This review examines the characteristics and function of ApoE described in both AD and cancer to assimilate evidence for its potential contribution to mechanisms that may underly the reported inverse association between the two conditions." (PMID 40149482, 2025). "These have been proposed as potential molecular mechanisms’ to explain the apparent inverse correlations between AD and cancer but little has been investigated surrounding APOE, despite the fact that its product (ApoE) modulates these molecules and has such a profound effect in AD." (PMID 40149482, 2025). "However, as investigations into the mechanisms related to malignant tumors in lipid metabolism have progressively increased over the years, attention has been directed towards the relationship between ApoE and cancer." (PMID 40495209, 2025). "Lifestyle-related factors might mediate the relationship between the apoE isoform and long-term cancer-related toxicity." (PMID 41465180, 2025). "ApoE isoforms may also moderate the influence of lifestyle modification and cancer treatment-related toxicities on cognition." (PMID 41465180, 2025).
cancer (continued). "Of the genetic risk factors relevant to most cases of AD, the most well-known with the strongest contribution to risk is APOE, specifically the ε4 variant, whereas for cancer risk, APOE has not featured as a significant genetic contributor to risk." (PMID 40149482, 2025). "Given the vital role of the interplay between exhausted CD8+ T cells and APOE+ macrophages in cancer immunotherapy, we conducted a cell‐to‐cell communication analysis to explore whether they interact with each other." (PMID 40492378, 2025). "This specific neutrophil subset exhibited spatial interactions with ApoE+ cancer (Cluster 18)." (PMID 39695088, 2024). "The three cell components within the lung metastatic niche, including CD163+ macrophages, neutrophils, and endothelial cells, expressed elevated levels of ApoE, leading to the secretion of various protumorigenic molecules that promote cancer cell growth in the lung." (PMID 39695088, 2024). "In addition, cell components of the TME, including macrophages, neutrophils, and endothelial cells, contributed to the remodeling of the TME and interactions with cancer cells when they expressed higher levels of lipid metabolism protein, ApoE." (PMID 39695088, 2024). "Recently, APOE has garnered attention in the field of cancer." (PMID 38566155, 2024). "Additionally, M2 macrophage-derived exosome was revealed to confer cancer cell resistance to ICT via apolipoprotein E (ApoE)-mediated downregulation of MHC-I." (PMID 38802766, 2024). "APOE+ TAMs may secrete factors that induce MMP7 expression in nearby cancer cells, enhancing their invasive capabilities." (PMID 39187937, 2024). "However, more than 20% carcinoma was found in ApoE−/− mice, indicating that the carcinogenesis rate was significantly higher in the hypercholesterolemic mice than in WT mice." (PMID 38755702, 2024). "More recently, there has been some evidence that APOE e2 may protect against CRCD in cancer survivors." (PMID 37296840, 2023). "In subgroups with higher APOE mRNA expression, most steps of the cancer immune cycle are activated." (PMID 38054821, 2023). "Moreover, we evaluated the impact of APOE mRNA expression on the cancer immunity cycle, which encompasses seven critical steps representing the anticancer immune response." (PMID 38054821, 2023). "APOE has emerged as a crucial player in various cancer types, with diverse roles in each context." (PMID 38054821, 2023). "However, the role of APOE in PTC primarily revolves around modulating the inflammatory response in this subset of cancer patients." (PMID 38067270, 2023). "In the current results, Macro_APOE/CTSZ is revealed to constitute the major source of cysteine cathepsin expression in cancer, which may be important for the functional differentiation and immunosuppressive properties of TAM." (PMID 36587392, 2023). "The function of APOE in cancer is multifaceted and depends on the specific situation." (PMID 38054821, 2023). "This aroused the speculation that the elevated ApoE could provide more cholesterol for the actively growing cancer cells." (PMID 36506554, 2022). "Being aware that inflammatory processes are also involved in carcinogenesis, it can be hypothesized that ApoE could potentially influence cancer development." (PMID 35892323, 2022). "The DFS and OS analyses also indicate the different roles played by APOE across cancer types." (PMID 37304007, 2022). "More specifically, we testes the hypothesis that apoE isoform modulates cancer- and cancer treatment-related side effects and symptoms in response to exercise intervention." (PMID 36441715, 2022). "Furthermore, APOE expression in cancer patients resistant to αPD-1 treatment significantly exceeded that in the sensitive group." (PMID 36147474, 2022).
cancer (continued). "The functions of APOE co-expressed genes were mainly enriched in adaptive immune response, protein-lipid complex subunit organization, actin cytoskeleton reorganization, cell chemotaxis, protein activation cascade and transcriptional misregulation in cancer." (PMID 35371313, 2022). "Previous studies report that APOE is mainly responsible for metabolism and redistribution of cholesterol, whereas recent studies report that its expression is upregulated and exerts biological functions in various cancers." (PMID 35090515, 2022). "Through this study, we aimed to investigate whether different APOE genotypes affect CVD and cancer in a southern China population by exploring the possible association of APOE polymorphisms between CVD and cancer patients." (PMID 36057714, 2022). "In order to further explore the potential mechanism of the five key genes (APOC1, APOC1P1, ISYNA1, C7orf61 and APOE) and whether these genes functioned through common cancer pathways, we analyzed them using the GSCALite platform by pathway activity module." (PMID 35371313, 2022). "Recent studies have revealed that the inflammatory ApoE effect may play a significant role in various cancer development." (PMID 35892323, 2022). "We tested the hypothesis that APOE genotype influences cancer treatment related side effects and symptoms as well as response to exercise intervention." (PMID 36441715, 2022). "APOE is an important marker of cancer, its overexpression in NSCLC has been reported before." (PMID 35681609, 2022). "Less is known regarding the role of apoE isoform in influencing cancer survivorship." (PMID 36441715, 2022). "The expression of APOE was also examined in the pre-treatment puncture samples of 19 carcinoma patients having received clinical αPD-1 treatment, and as revealed from the results, the expression of APOE in the αPD-1 resistant group significantly exceeded that in the αPD-1 sensitive group." (PMID 36147474, 2022). "Cancer-secreted APOE was regard as an anti-angiogenic and metastasis-suppressive factor." (PMID 34249502, 2021). "While it is unclear exactly how APOE is involved in cancer development, it may affect the metabolism of cancer cells by regulating lipid homeostasis." (PMID 34063271, 2021). "Potential therapeutics based on APOE biology could mitigate these detrimental cognitive effects for those receiving chemotherapy, emphasizing that the APOE genotype could help in developing personalized cancer treatment regimens." (PMID 33352780, 2020). "In addition, ADOR1 and LPAR5 exhibited a hypomethylation state in the cancer group, but APOE showed a hypermethylation state in PTC samples." (PMID 32766727, 2020). "The role of ApoE in cancer cells is unclear and limited studies have addressed it." (PMID 31788012, 2019). "Thus, we investigated the role of TREM-1 on ApoE KO mice originated NK cell mediated cytotoxicity for cancer cells." (PMID 31275318, 2019). "Similarly, exposure of NT2 (NTera-2) “preneuronal” carcinoma cells to the inflammatory cytokine IL-1β elicited upregulation of ApoE and of p38/MAPK innate-immune signaling—responses that were fully blocked by PNR502." (PMID 31920540, 2019). "Further studies are needed to evaluate whether targeting ApoE or inhibiting exosomes released by TAMs can be manipulated to inhibit cancer metastasis." (PMID 29567987, 2018). "Also, cancer cells displayed high level of ApoE in a mouse model of high grade serous ovarian carcinoma." (PMID 29458390, 2018). "Several studies reported on a role of the ApoE gene in cancer." (PMID 24497847, 2014). "Age of AD onset analysis stratifying for APOE ε4 still found CA+ associated with later age of AD onset, supporting the assertion that APOE ε4 does not appear to be driving the inverse association of cancer and AD." (PMID 25400589, 2014).